PRDX3 (peroxiredoxin 3)
Description:
Thiol-specific peroxidase that catalyzes the reduction of hydrogen peroxide and organic hydroperoxides to water and alcohols, respectively. Plays a role in cell protection against oxidative stress by detoxifying peroxides. Acts synergistically with MAP3K13 to regulate the activation of NF-kappa-B in the cytosol. Required for the maintenance of physical strength (By similarity).
Synonyms: AOP-1; Prx-III; AOP1; MER5; SP-22; HBC189; PPPCD; PRO1748; SCAR32
Tractability: Antibody: its Gene Ontology location is reachable by antibodies, with high confidence. PROTAC: ubiquitination databases record sites on it; its protein half-life has been measured.
Target class: Enzyme; Oxidoreductase
Gene: Protein-coding gene on chromosome 10 (119,167,699 to 119,178,865, reverse strand). Ensembl gene ENSG00000165672.
Subcellular location: Mitochondrion; Cytoplasm; Early endosome
Subcellular location (Human Protein Atlas): Mitochondria; Vesicles
Pathways (Reactome):
Cellular responses to stimuli: Detoxification of Reactive Oxygen Species
Gene Ontology:
Molecular function: cysteine-type endopeptidase inhibitor activity involved in apoptotic process; identical protein binding; protein binding; protein kinase binding; thioredoxin peroxidase activity; thioredoxin-dependent peroxiredoxin activity; NADH-dependent peroxiredoxin activity; antioxidant activity; oxidoreductase activity; peroxiredoxin activity
Biological process: cellular response to oxidative stress; cellular response to reactive oxygen species; hydrogen peroxide catabolic process; mitochondrion organization; negative regulation of apoptotic process; negative regulation of kinase activity; positive regulation of canonical NF-kappaB signal transduction; positive regulation of cell population proliferation; regulation of mitochondrial membrane potential; response to hydrogen peroxide; response to oxidative stress; myeloid cell differentiation; response to lipopolysaccharide; cellular oxidant detoxification
Cellular component: cytoplasm; cytosol; early endosome; mitochondrion; protein-containing complex; mitochondrial matrix
Genetic constraint (gnomAD): Loss-of-function variants: 19 observed, 27.61 expected, observed/expected ratio (o/e) 0.69, 90% interval 0.48 to 1.01. The upper end of that interval is the gene's LOEUF score, 1.01, which puts it in group 4 of 6, group 1 being the genes least tolerant of losing a copy. Missense variants: 318 observed, 318.74 expected, observed/expected ratio (o/e) 1, 90% interval 0.91 to 1.1. Synonymous variants: 121 observed, 120.95 expected, observed/expected ratio (o/e) 1, 90% interval 0.86 to 1.16.
Homologues: Orthologues: chimpanzee PRDX3 (100% identical), macaque PRDX3 (98% identical), dog PRDX3 (91% identical), pig PRDX3 (91% identical), guinea pig PRDX3 (89% identical), mouse Prdx3 (86% identical), rat Prdx3 (78% identical), zebrafish prdx3 (72% identical), Drosophila melanogaster Prx3 (52% identical). Paralogues in human: PRDX4 (55% identical), PRDX2 (50% identical), PRDX1 (48% identical), PRDX6 (21% identical).
Diseases named in the same sentence as PRDX3 in open-access papers:
PRDX3 is named in the same sentence as 128 diseases in open-access papers, as found by Europe PMC text mining. Sharing a sentence is not in itself a finding about the gene and the disease. The quoted sentences say what the papers report.
breast carcinoma (14 papers, 2007 to 2025). "Another study also revealed that higher mRNA expression of PRDX1/2/4/5/6 was correlated with worse prognosis, while high levels of PRDX3 were associated with favorable prognosis of patients with breast cancer." (PMID 32908916, 2020). "In breast cancer, the upregulated expression of Prdx3 is associated with the development of resistance to the drug doxorubicin." (PMID 31500275, 2019). "A previous report described that both Prdx3 and 4 have been associated with the presence of hormone receptors in breast cancer patients." (PMID 21347291, 2011). "Our findings show that PRDX3 enhances cellular processes associated with breast cancer spread." (PMID 38321552, 2024). "Upregulated expression of PRDX3 has been observed in colon cancer stem cells, prostate cancer cells, hepatocellular carcinoma, medulloblastoma, and breast cancer cells." (PMID 40462224, 2025). "Knockdown of PRDX3 expression in triple negative basal B MDA-MB-231 and BT-549 breast cancer cells inhibited cell migratory and invasive potential, demonstrating the oncogenic role of PRDX3 in promoting tumour progression." (PMID 38321552, 2024). "In conclusion, the present work demonstrates that PRDX3 plays an essential role in promoting breast cancer migration and invasion, via ERK-mediated upregulation of MMP-1." (PMID 38321552, 2024). "Meanwhile, depletion of PRDX3 expression by transient siRNA significantly reduced cell invasion but had an equivocal effect on migration in BT-549 breast cancer cells." (PMID 38321552, 2024). "GOBO analysis also showed that the PRDX3 gene is differentially expressed in breast cancer cell lines, with the highest expression in basal breast cancer cell lines." (PMID 38321552, 2024). "In this study, we observed that PRDX3 contributed to the invasive ability in two breast cancer cell lines, via upregulation of MMP-1, which is due to the activation of ERK/AP1 signaling, as demonstrated by multi-pathway reporter array and western blotting." (PMID 38321552, 2024). "In this regard, administration of an ERK specific inhibitor was shown to reduce MMP-1 expression, and possibly metastasis in PRDX3-overexpressing breast cancer." (PMID 38321552, 2024). "Previous studies report that the augmented levels of PRDX1, PRDX3 and PRDX6 were associated with cisplatin resistance status for erythroleukemia, breast cancer and ovarian carcinoma." (PMID 34246267, 2021). "In many other cancers, such as breast cancer, ovarian cancer, and erythroleukemia, chemoresistance is developed by the upregulated expression of Prdx1, Prdx3, and Prdx6." (PMID 31500275, 2019). "FoxM1 downregulates ROS levels by stimulating expression of ROS scavenger genes, such as MnSOD, catalase and PRDX3; the Nrf2-Prx I axis is important in human lung-cancer, prostate-cancer, colon-cancer, and breast-cancer development." (PMID 27517622, 2016). "PRDX3 levels are increased in prostate cancer, lung cancer, breast cancer and hepatocellular caricinoma." (PMID 26061816, 2015). "4-amino-5-(4-chlorophenyl)-7-(t-butyl)pyrazolo[3, 4-d]pyrimidine (PP2) induces apoptosis and decreases the expression of PRDX3 in human breast cancer MCF-7 cells." (PMID 26061816, 2015). "Especially for PRDX3 increased expression was found in human breast cancer, lung cancer, mesothelioma and hepatocellular carcinomas." (PMID 21760917, 2011). "A recent study indicates that activation of the extracellular signal-regulated kinase (ERK) signaling may also result in the MMP1 transcriptional activation in the peroxiredoxin 3 (PRDX3)-overexpressed breast cancer cells." (PMID 39590789, 2024). "Taken together, these results suggest that PRDX3 regulate fundamental processes involved in the metastatic cascade, may therefore play a crucial role in the metastasis of breast cancer." (PMID 38321552, 2024).
breast carcinoma (continued). "Targeted inhibition of ERK signaling may be able to inhibit metastasis in PRDX3-overexpressed breast cancer- a personalized oncology approach that would advance individualization of breast cancer therapy." (PMID 38321552, 2024). "Moreover, immunohistochemical staining of breast cancer tissues revealed a positive correlation between PRDX3 and MMP-1 expression in both epithelial and stromal parts of the tissues." (PMID 38321552, 2024). "Secondly, we did not perform any in vivo experiments, which could provide additional insights pertaining to the role of PRDX3 in pre-clinical models of breast cancer progression." (PMID 38321552, 2024). "In this study, we provide evidence for the first time that PRDX3 could regulate cellular signaling pathways associated with Matrix Metalloproteinase-1 (MMP-1) expression and activity in breast cancer progression." (PMID 38321552, 2024). "Additionally, PRDX3 is highly expressed in tumor tissues of breast cancer, cervical cancer, liver cancer and prostate cancer." (PMID 34246267, 2021). "Noh and colleagues reported that PRDX1, PRDX2 and PRDX3 were overexpressed in breast cancer tissues, suggesting that PRDXs had a proliferative effect and might be related to cancer development or progression." (PMID 17980029, 2007). "Hence, in this study, we investigated the possible mechanism of PRDX3 in breast cancer progression." (PMID 38321552, 2024). "Notably, this phenomenon may be attributed to the activation of MMP-1, which is observed to be upregulated by PRDX3 in the breast cancer cells." (PMID 38321552, 2024). "Overexpression of PRDX3, on the other hand, significantly enhanced migration and invasion in MDA-MB-231 breast cancer cells." (PMID 38321552, 2024). "Our current results also showed that PRDX3 can exert its invasive potential, via upregulation of MMP-1 in breast cancer cells." (PMID 38321552, 2024). "According to the Gene expression-based Outcome for Breast cancer Online (GOBO) analysis, the PRDX3 gene is highly expressed in basal B breast cancer cell lines in comparison with the basal A and luminal subtypes." (PMID 38321552, 2024). "Stable shRNA-mediated silencing of the PRDX3 showed a significant reduction in the cell migratory and invasive potential in MDA-MB-231 breast cancer cells." (PMID 38321552, 2024). "To validate our results in the clinical setting, we analyzed the expression of PRDX3 and MMP-1 in 152 paired breast cancer patient samples." (PMID 38321552, 2024). "Taken together, through maintaining and promoting the oncogenic AP-1 activation, PRDX3 may contribute to the activation of AP-1 downstream signaling pathways target MMP-1, that is critical for the malignancy of human breast cancer cells." (PMID 38321552, 2024). "PRDX3 has also been documented to be involved in tumor progression in several human cancers, however its role in breast cancer is not fully explored." (PMID 38321552, 2024). "In breast cancer, miR-567 could inhibit cancer cell proliferation and migration by regulating KPNA4; miR-567 could also regulate autophagy and reverse trastuzumab resistance via ATG5 in breast cancer; in renal cell carcinoma, miR-567 could inhibit cancer cells progression by regulating PRDX3." (PMID 34226531, 2021). "Karihtala and colleagues observed that staining for PRDX2 and PRDX6 was negative in half of breast cancer cases, whereas PRDX1, PRDX3, PRDX4 and PRDX5 showed stronger expression levels." (PMID 17980029, 2007).
prostate carcinoma (13 papers, 2011 to 2025). A carcinoma that arises from epithelial cells of the prostate gland. "Early studies demonstrated elevated Prdx3 expression in prostate cancer, where low Prdx3 levels correlate with significantly improved patient survival." (PMID 40837016, 2025). "PRDX proteins are usually upregulated in prostate cancer, with PRDX3 and 4 being overexpressed in metastatic prostate cancer, thus helping them cope with oxidative stress and cell survival." (PMID 37627612, 2023). "PRDX3 is overexpressed in several types of cancer, including prostate cancer, protecting cells against apoptosis." (PMID 36672191, 2023). "Both peroxiredoxin 1 (PRDX 1) and peroxiredoxin 3 (PRDX 3) proteins were significant and their overexpression in prostate cancer has been proposed to be linked to cancer initiation and progression." (PMID 37627612, 2023). "Inhibition of both miR-23b in prostate cancer and leukemia and miR-26a-5p in leukemia can scavenge excessive levels of ROS by increase of PRDX3 gene expression." (PMID 34199590, 2021). "It was reported that PRDX3 is overexpressed in prostate cancer and promotes cancer cell survival by protecting cells from oxidative stress." (PMID 29113303, 2017). "It was reported that PRDX3 is overexpressed in prostate cancer and its overexpression promotes cancer cell survivals by protecting cells from oxidative stress." (PMID 29113303, 2017). "Additionally, PRDX3 has been found overexpressed in castration-resistant prostate cancer cells, which culminates in promoting cell survival by protecting them from oxidative stress." (PMID 36672191, 2023). "PRDX3 acts as an oncogene in hepatocellular carcinoma, prostate cancer and renal cell carcinoma." (PMID 35350568, 2022). "PRDX3 levels are elevated in prostate cancer and reduced by miR-23b." (PMID 34199590, 2021). "Protein network analysis and clustering of differentially expressed proteins revealed new targets such as DDAH1, ARG2, EIF4A3, Par4, PPA2, Prdx3 and Prdx4, which need further validation to define their potential application in clinical relevance in prostate cancer." (PMID 21347291, 2011). "Since prostate tumors are also hormone dependent, we speculate on a role of Prdx3 and 4 controlling tumor proliferation, apoptosis and dissemination of tumor cells during prostate cancer progression." (PMID 21347291, 2011). "Regarding the proteomics, IHC staining analysis of prostate tissue or PCa tissue from the Human Protein Atlas database showed that higher staining of PRDX3 and PRDX5 was found in higher grade of prostate cancer." (PMID 40281661, 2025). "Peroxiredoxin 3 (PRDX 3) overexpression has been demonstrated to counteract senescence and promote tumor survival in prostate cancer." (PMID 37627612, 2023). "Peroxiredoxins 3 (PRDX3) and PRDX4 have been found to be upregulated in prostate cancer tissue and impact the cell growth of prostate tumors." (PMID 24739220, 2014). "In conclusion, the current study identified potential novel biomarkers for prostate cancer development and/or progression such as eIF4A3, DDAH1, ARG2, Prdx3, and Prdx4 from proteomic data using systems biology approach." (PMID 21347291, 2011).
hepatocellular carcinoma (12 papers, 2011 to 2025). A malignant tumor that arises from hepatocytes. "According to previous publications, high expression PRDX3 is associated with advanced malignant phenotype and worse prognosis in hepatocellular carcinoma, endometrial cancer, and medulloblastoma." (PMID 32382548, 2020). "The upregulated expression of Prdx3 is associated with an enhanced expression of ATP synthase and increased ATP production in hepatocellular carcinoma, and it plays a role in tumor growth and progression." (PMID 31500275, 2019). "Furthermore, PRDX3 overexpression was strongly associated with the progression of hepatocellular carcinoma; patients with high serum PRDX3 levels had a shorter median survival time when compared to those with low serum PRDX3 level." (PMID 30104402, 2018). "An upregulated expression of Prdx3 and Prdx5 has been reported in different cancer types, such as breast, ovarian, endometrial, and lung cancers, as well as in Hodgkin’s lymphoma and hepatocellular carcinoma." (PMID 31500275, 2019). "Interestingly, women with hepatocellular carcinoma (HCC) exhibit elevated expression of Prdx3, whereas men—of Prdx1." (PMID 34207367, 2021). "Knockdown of PRDX3 inhibited the growth of hepatocellular carcinoma cells." (PMID 32729669, 2020). "FOXM1 is known to regulate the expression of important AOS genes including catalase, superoxide dismutase 2 (SOD2) and PRDX3 which we found to be highly overexpressed in multiple cancers (group 6), at the exception of catalase, exclusively overexpressed in hepatocellular carcinoma (group 3)." (PMID 24342878, 2013). "Low levels of Prdx3 can be regarded as a negative prognostic factor for patients with HBV or HCV-related hepatocellular carcinoma." (PMID 34207367, 2021). "Furthermore, PRDX1 level was found to predict poor patient survival in non-small cell lung, ovarian, and breast cancers, and PRDX3 and PRDX4 expression were correlated with poor prognosis in hepatocellular carcinoma and squamous cell carcinoma respectively." (PMID 24342878, 2013).
colon cancer (7 papers, 2016 to 2025). "In fact, PRDX3 knockdown combined with 5-FU increased cell death and tumor suppression in colon cancer." (PMID 28432271, 2017). "In colon cancer, PRDX3 was overexpressed in colon cancer stem cells and essential for maintenance of and survival of colon cancer stem cells." (PMID 27958341, 2016). "Studies have demonstrated that PRDX3 expression is particularly elevated in CSC-enriched populations, such as CD133+ colon cancer stem cells, where it facilitates tumor progression and metastasis." (PMID 40608151, 2025). "In a study on colon cancer, suppression of FOXM1 led to reduced PRDX3 expression in CD133+ CSCs, resulting in decreased tumor sphere formation and sensitization to chemotherapy." (PMID 40608151, 2025).
Obesity (7 papers, 2013 to 2023). Accumulation of substantial excess body fat. "Altogether, these findings indicated a role for PRDX3 genetic variations and fat intake in the modulation of BMI and obesity risk." (PMID 24562334, 2014). "The impact of PRDX3 genetic variations on obesity has been investigated in only one nutrigenomic study, in which it was found that four SNPs in the PRDX3 gene and the haplotype they formed were associated with higher BMI and obesity in Japanese people, when combined with a high-fat diet (HFD)." (PMID 24562334, 2014). "Molecular pathway analysis of LRRK2 reveals direct links between LRRK2 and the thioredoxin system, which interacts with PRDX3, TXNIP and TXNRD1, proteins that are associated with nutrient sensing, adiposity and human obesity." (PMID 23799078, 2013). "Several components of the thioredoxin system are closely linked to LRRK2, including PRDX3, TXNIP, and TXNRD1, which have been identified in recent years as risk factors for obesity and diabetes in human subjects, and as nutrient sensing mechanisms and controlling factors of adipogenesis in mice." (PMID 23799078, 2013). "Indeed, PRDX3 is expressed in mature adipocytes and has been observed to be decreased in obesity." (PMID 27023799, 2016).